INS (insulin)
Diseases named in the same sentence as INS in open-access papers (continued):
Sharing a sentence is not in itself a finding about the gene and the disease.
diabetes (continued). "Diabetes is generally comprised of several subcategories such as type 1 diabetes mellitus which demonstrated by absolute insulin deficiency caused by cell-specific autoimmune destruction of the insulin producing beta cells in the pancreas." (PMID 28497094, 2017). "Among those with diabetes, ID was associated with higher occurrence of prescription of insulin combination drugs and sulfonylureas, but lower occurrence of prescription of dipeptidyl peptidase (DPP) 4-inhibitors and exenatide/liraglutide." (PMID 29169334, 2017). "Approximately 50% of patients are diabetic or insulin deficient at the time of cancer diagnosis; of these, half are diagnosed within three years of diabetes diagnosis." (PMID 28272344, 2017). "At age 45 years, the remaining lifetime risk was 48.7% for prediabetes, 31.3% for diabetes, and 9.1% for insulin use." (PMID 29064009, 2017). "Hypoglycemia is an important acute complication in diabetes mellitus patients treated with insulin or sulfonylurea, which can cause severe brain damage." (PMID 28335557, 2017). "We searched the GEO database and identified 27 gene expression datasets from different tissues, of which 14 datasets were related to 13 expression studies of diabetes states and 11 datasets were linked to five expression studies of insulin responses." (PMID 28117714, 2017). "In the modern era of aggressive cardiovascular risk factor control in diabetes, this study reveals higher mortality only in insulin‐treated diabetic patients following PCI for stable coronary artery disease and acute coronary syndrome." (PMID 28029209, 2017). "Decreased levels of CREB protein and the active form of CREB (phosphoserine 133 CREB, pCREB) in medial VSMCs have been observed in rodent models of insulin-resistant and insulin-deficient diabetes-associated vascular disease." (PMID 28855544, 2017). "Insulin gene (INS) mutations (MODY 10) cause permanent neonatal diabetes (PNDM) and are a very occasional cause of diabetes diagnosed in childhood or adulthood." (PMID 28095440, 2017). "To date, several studies that have demonstrated an association between AD and diabetes have revealed that the common risk factors include insulin resistance, sleep disturbances, blood brain barrier (BBB) disruption, and altered glucose homeostasis." (PMID 28764741, 2017). "Previous studies concluded that delayed nadir for post-load glucose level indicated a higher insulin resistance combined with a reduction in insulin secretion–leading to a higher risk of diabetes." (PMID 29216249, 2017). "After 8 weeks of HFD feeding, mice exhibited diabetes, with elevated insulin and glucose concentrations associated with body weight gain." (PMID 27983752, 2017). "The association between obesity and diabetes and its biological mechanisms have gained further support from the intervention studies in which weight reduction improved insulin sensitivity and reduced diabetes risk." (PMID 28786989, 2017). "The main event in the etiology of diabetes is the loss of pancreatic islet ß cells with concomitant decline of insulin secretion." (PMID 28405347, 2017). "Neonatal diabetes is typically defined as diabetes with onset before the age of 6 months, but some INS mutation patients develop diabetes later in childhood or young adulthood." (PMID 28951826, 2017). "A significant association between diabetes and AD has also been reported by linking insulin and glucose metabolism load to β-amyloid levels in AD." (PMID 28070499, 2017). "Differences in insulin level have recently been reported to be a risk factor of cardio-metabolic health, thus implicating MZ not only in diabetes but also in cardio-metabolic health." (PMID 28804442, 2017). "The frequencies of all and severe hypoglycemia demonstrated a significant positive association with the duration of diabetes (p = 0.000 for both), daily insulin dose (p = 0.003 and 0.000, resp)." (PMID 28913365, 2017).
diabetes (continued). "Reported data represents the observed association between pre-existing use of injectable insulin before breast cancer diagnosis and the T-helper 1 and 2 produced cytokine profiles upon cancer diagnosis in women with both breast cancer and diabetes mellitus." (PMID 28275667, 2017). "Reported data represents the observed association between use of injectable insulin preceding breast cancer and the growth factor profiles at the time of cancer diagnosis in women with diabetes mellitus." (PMID 28239632, 2017). "Type 2 diabetes is characterized by high levels of insulin, which are presumed to be a driving factor of diabetes-associated cancer." (PMID 28521289, 2017). "Diabetes mellitus is a chronic disease associated with abnormally high blood glucose levels, and occurs when pancreatic β-cells fail to meet insulin demand due to loss of β-cell mass and function." (PMID 28208663, 2017). "One remarkable feature of diabetes is the metabolic imbalance due to deficient insulin production or inhibited signaling in target cells." (PMID 28842605, 2017). "Our meta-analysis showed that PGRMC1, HADH, IRS1 and MPST were the four tissue non-specific genes presenting differential expression association with the diabetes or insulin response." (PMID 28117714, 2017). "Diabetes is a serious, chronic disease caused by either insufficient insulin production from the pancreas (type 1), or when the body cannot effectively utilize the insulin it produces (type 2) (World Health Organization [WHO], 1999)." (PMID 28642702, 2017). "Although we focused on the effects of CE on insulin secretion in this paper, further study was needed to evaluate other underlying mechanisms of its anti-diabetes effects." (PMID 28091547, 2017). "The axis of insulin/SREBP-1/transgelin-2 links the association between diabetes and PDAC, suggesting that this signaling pathway represents new therapeutic targets and molecular markers for this subgroup of PDAC." (PMID 28521289, 2017). "In the first case, a 29-year-old woman with sudden hemorrhage in the left eye who had associated diabetes; under control by insulin injections, had abortion 5 days after receiving bevacizumab." (PMID 28979321, 2017). "Yet while the same components of the negative feedback loop that regulates blood sugar, glucose and insulin, are implicated in both, untreated Type 1 and Type 2 diabetics have distinct—and, in some cases, opposite—clinical features." (PMID 28439230, 2017). "Type 1 diabetes mellitus is an autoimmune disease resulting from the destruction of insulin-secreting β-cells of the pancreas causing a substantial β-cell deficit." (PMID 29244751, 2017). "It is well known that poor glycemic control is a risk factor for the development and progression of DR, and vitamin D deficiency has been shown to impair insulin synthesis and secretion in animal models of diabetes." (PMID 28335514, 2017). "American Diabetes Association accurately defined diabetes mellitus as “a group of metabolic diseases characterized by hyperglycemia resulting from defects in insulin secretion, insulin action, or both”." (PMID 28386567, 2017). "The American Diabetes Association defines diabetes as a group of metabolic diseases characterised by hyper-glycemia, which results from defects in insulin secretion, insulin action, or both." (PMID 29250612, 2017). "As tacrolimus increases the risk of diabetes via reductions in insulin secretion and inhibition of insulin gene expression stimulus by hyperglycemia, long term monitoring blood glucose level is important for patients with IMN treated with this agent." (PMID 28898290, 2017). "An underlying cause of beta-cell decay in diabetes is oxidative stress, which markedly affects the insulin producing pancreatic cells due to their poor antioxidant defence capacity." (PMID 28542222, 2017). "Streptozotocin (STZ) is a toxin for pancreatic β-cell, which can construct a model of insulin deficient diabetes through intraperitoneal or intravenous injection." (PMID 29209211, 2017).
diabetes (continued). "Diabetes mellitus is one of the most common metabolic diseases spread all over the world, which results in hyperglycemia caused by the breakdown of insulin secretion or insulin action or both." (PMID 29036909, 2017). "Alloxan causes diabetes by rapid depletion of pancreatic β-cells leading to inflammation and sustained hyperglycemia secondary to a reduction in insulin release into circulation." (PMID 28862678, 2017). "For example, insulin-reactive TCR 12-4.1 isolated from pancreatic islets of NOD mice exhibits barely detectable reactivity to insulin in vitro, but causes spontaneous diabetes in 50–80% of mice." (PMID 29312143, 2017). "Reported data represents the observed association between insulin secretagogues׳ utilization and the adipokine profiles at the time of breast cancer diagnosis in women with diabetes mellitus." (PMID 27995161, 2017). "They reported that elevated levels of glucose, free fatty acids, and inflammatory cytokines caused by diabetes and insulin resistance selectively inhibited insulin’s antiatherogenic actions via the IRS/PI3K/Akt pathway, but not the Grb/Shc/MAPK pathway." (PMID 29066788, 2017). "Protective alleles of the IDDM2 diabetes susceptibility locus promote higher levels of insulin expression in the thymus, which would promote more robust negative selection of insulin-reactive T cells." (PMID 29259578, 2017). "When eight NOD CD4 T cell-derived TCRs with variable affinity for insulin InsB9–23 epitope were compared for their ability to drive spontaneous diabetes, high- and low-affinity T cells were similarly pathogenic." (PMID 29312143, 2017). "Direct studies of epigenetic changes have implicated changes associated with insulin secretion and diabetes risk." (PMID 28815391, 2017). "Diabetes is characterized by defective control of blood glucose resulting from an absolute or relative deficiency of insulin, the hormone released from pancreatic beta-cells." (PMID 29403437, 2017). "Our results indicating increased insulin sensitivity are interesting in relation to previous concerns about the possibility that selenium supplementation should cause an increased risk of diabetes." (PMID 28609475, 2017). "On multivariable linear regression analysis, the presence of premorbid insulin-requiring diabetes was independently associated with lower admission c-peptide level (−0.9 nmol/l, 95% CI −1.8 to −0.04, P = 0.04)." (PMID 28497374, 2017). "Lower SHBG levels have been widely associated with a higher risk of metabolic conditions, including diabetes, cholesterolemia, and obesity, and with adverse changes in fasting insulin, glucose, and BMI." (PMID 29075555, 2017). "The differential methylation of MSI2 at chr17:55484635 was associated with diabetes-related traits, in particular with insulin sensitivity (QUICKI, p value = 2.20E-16) and resistance (HOMA-IR, p value = 1.177E-07)." (PMID 28542303, 2017). "Higher EN-RAGE levels were associated with an increased risk of incident pre-diabetes, whereas higher IL13 levels were associated with a decreased risk of pre-diabetes, incident type 2 DM and need for insulin therapy." (PMID 28258520, 2017). "Insulin-dependent diabetes mellitus is caused by dysregulated immune cell destruction of the insulin-generating pancreatic islet β-cells." (PMID 28396662, 2017). "Human insulin is a pivotal protein hormone controlling metabolism, growth, and aging and whose malfunctioning underlies diabetes, some cancers, and neurodegeneration." (PMID 28348075, 2017). "Impairment in insulin production or loss of insulin sensitivity in insulin target tissues causes diabetes mellitus." (PMID 28072841, 2017). "Reported data represents the observed association between use of injectable insulin preceding breast cancer and the hematopoietic cytokine profiles at the time of cancer diagnosis in women with diabetes mellitus." (PMID 28275672, 2017).
diabetes (continued). "Iron overload causes DM and is present in target organs of diabetes, such as the kidneys, while iron depletion upregulates glucose uptake and insulin signaling in liver and decreases kidney inflammation in experimental diabetes." (PMID 28060743, 2017). "Obese cats are up to four times more likely to develop diabetes mellitus as obesity is associated with a reduction in insulin sensitivity." (PMID 29140289, 2017). "It is logical to assume that with a modest loss of insulin secretory capacity, additional factors that predispose to reduced insulin secretion and insulin sensitivity would predispose to clinical diabetes." (PMID 28829396, 2017). "Diabetes is caused by defects in insulin secretion and/or action, resulting in chronic hyperglycemia and metabolic diseases." (PMID 26986757, 2016). "QoL was associated with the use of insulin and desired glycaemic control, longer diabetes duration, worry about diabetes, and diabetes complications." (PMID 27695086, 2016). "Insulin, a hormone that controls blood glucose levels, is implicated in diabetes mellitus, a disease characterized by elevated levels of blood glucose over a prolonged period." (PMID 27224490, 2016). "Resistance to the central actions of leptin or insulin is linked to the emergence of obesity and diabetes mellitus." (PMID 27812350, 2016). "In fact, diabetes comes from a metabolic disorder caused by the body’s inability to produce insulin, a hypoglycemic hormone secreted by the pancreatic β-cells of the islets of Langerhans." (PMID 27057112, 2016). "MiR-33a has been reported to be implicated in diabetes due to its regulation of insulin signaling and fatty acid metabolism." (PMID 27613243, 2016). "The United Kingdom Prospective Diabetes Study (UKPDS) showed that total weight gain was associated with total exogenous insulin dose." (PMID 27777901, 2016). "Maturity onset diabetes of the young (MODY) is a monogenic form of diabetes caused by a mutation in at least one of the genes known to affect insulin production or secretion." (PMID 26059258, 2016). "Mitochondrial dysfunction is closely associated with impaired insulin sensitivity and diabetes, and mitochondrial deficiency contributes to mitochondrial dysfunction." (PMID 27196053, 2016). "After adjustment of confounders, diabetes and hypertension status, and the use of insulin were associated with PAD." (PMID 27093857, 2016). "The social stigma attached to diabetes and insulin therapy was associated with embarrassment on the part of the patient." (PMID 27230479, 2016). "Defects in insulin secretion and/or insulin resistance are generally considered as the two main pathophysiologic mechanism underlying the development of diabetes." (PMID 27992538, 2016). "The only aspect of diabetes history to be associated with the development of CS-CLD was the use of insulin (HR 9.08)." (PMID 26454513, 2016). "Type 2 diabetes mellitus is a metabolic disorder characterized by chronic hyperglycemia in association with insulin resistance, impaired relative and/or absolute insulin production, and altered glucagon secretion." (PMID 26697506, 2016). "This leads within a few weeks to symptoms of acute, insulin-deficient diabetes, with significant loss of body weight in all STZ injected rats." (PMID 27803936, 2016). "A recent study from Finland reported an even higher 46% increase in diabetes incidence associated with statins accompanied by both loss of insulin sensitivity and secretion." (PMID 26577796, 2016). "KCJN11 gene is critical in regulation of insulin and is known to be associated with type 2 diabetes mellitus." (PMID 27535653, 2016). "We found that the fasting insulin concentration and diabetes prevalence rose as BMI increased, and that insulin concentrations were inversely associated with verbal IQ score." (PMID 27642517, 2016). "This is consistent with prior studies linking decreased insulin clearance with an adverse metabolic profile and increased risk of diabetes." (PMID 27846285, 2016).
diabetes (continued). "The most significantly downregulated gene associated with insulin secretion and diabetes in WFS1‐deficient islets following Wfs1 was melastatin‐related transient receptor potential subfamily member 5 (Trpm5)." (PMID 27053292, 2016). "It comprises around 90% of people with diabetes mellitus that is caused by a combination of resistance to insulin action and an inadequate compensatory insulin secretory response." (PMID 27886206, 2016). "The comparatively similar effects of SFA versus carbohydrate on glucose-insulin homeostasis are consistent with their similar overall associations with both incident diabetes and cardiovascular events." (PMID 27434027, 2016). "Diabetes treatment with insulin was associated with an overall increased risk of breast cancer (OR 2.98; 95 % CI 1.26–7.01)." (PMID 25916213, 2016). "For EGIR-diagnosis, the highest risk of type 2 diabetes mellitus was associated with a combination of INS–DYSL–GLYC (HR 7.35; 95 % CI 5.92–9.13)." (PMID 27117940, 2016). "Similar to the beneficial roles of insulin treatment on sensory deficits associated with DN, insulin treatment has been shown to protect against late-stage diabetes-induced motor neuropathy as well." (PMID 28066166, 2016). "Other risk factors for DKD in diabetics include male sex, obesity, hypertension, inflammation, resistance to insulin, hypovitaminosis D, and dyslipidaemia." (PMID 28197499, 2016). "Diabetes Mellitus is a clinical syndrome, characterized by hyperglycemia caused by a relative or absolute deficiency of insulin at the cellular level." (PMID 28078249, 2016). "One implant is sufficient to prevent loss of animals due to ketoacidosis but enables to use the animals as type 1-like diabetes model to study the efficacy of glucose lowering drugs e.g. in combination with insulin." (PMID 27253523, 2016). "Dysfunction of insulin release from pancreatic islet β-cells is considered to be one of the causal factors in the etiology of type 2 diabetes mellitus (T2DM)." (PMID 28036092, 2016). "CpGs that were significantly associated with higher BMI, fasting glucose, fasting insulin, risk of diabetes, triglycerides, and risk of CHD were also associated with higher CRP levels." (PMID 27955697, 2016). "The stepwise progression towards type 2 diabetes involves increasing insulin resistance, although it is well established that only when combined with a simultaneous loss of compensatory hypersecretion of insulin does this lead to diabetes." (PMID 27344314, 2016). "The underlying treatment patterns differed from general diabetes cohorts with a remarkably high proportion of more than 50 % receiving insulin-based therapies which were associated with an increased probability of HbA1C levels >7 % (53 mmol/mol)." (PMID 27286816, 2016). "We saw similar relationships with BMI in our populations, with elevated BMI being associated with diabetes, increased insulin, and increased insulin resistance, as well as decreased adiponectin levels." (PMID 27830830, 2016). "In most studies, the Arg64/X variant coexisted with increased body mass (overweight or obesity), decreased insulin sensitivity and glucose control, and raised risk of metabolic syndrome and early onset of diabetes mellitus type 2." (PMID 27246401, 2016). "Higher educational and socioeconomic status was associated with better understanding of insulin use and complications related to diabetes." (PMID 26697499, 2016). "Type 1 diabetes mellitus is an autoimmune disease that results in an insulin deficiency, whereas type 2 diabetes mellitus is characterized by peripheral insulin resistance frequently in combination with a dysfunctional insulin production." (PMID 27223471, 2016). "Destroying the cells that produce insulin – known as β-cells – causes normal mice to develop diabetes." (PMID 27190125, 2016).